OPCML (opioid binding protein/cell adhesion molecule like)
Description:
Binds opioids in the presence of acidic lipids; probably involved in cell contact.
Synonyms: OBCAM; IGLON1; OPCM
Tractability: Antibody: its Gene Ontology location is reachable by antibodies, with high confidence; UniProt places it where antibodies can reach, with medium confidence; UniProt predicts a signal peptide or a membrane-spanning region. PROTAC: ubiquitination databases record sites on it; its protein half-life has been measured.
Gene: Protein-coding gene on chromosome 11 (132,414,977 to 133,532,501, reverse strand). Ensembl gene ENSG00000183715.
Subcellular location: Cell membrane
Pathways (Reactome):
Metabolism of proteins: Post-translational modification: synthesis of GPI-anchored proteins
Gene Ontology:
Molecular function: protein binding
Biological process: cell adhesion; heterophilic cell-cell adhesion; neuron recognition; regulation of synapse assembly
Cellular component: extracellular region; plasma membrane; postsynaptic density
Genetic constraint (gnomAD): Loss-of-function variants: 12 observed, 36.63 expected, observed/expected ratio (o/e) 0.33, 90% interval 0.21 to 0.53. The upper end of that interval is the gene's LOEUF score, 0.53, which puts it in group 2 of 6, group 1 being the genes least tolerant of losing a copy. Missense variants: 327 observed, 441.74 expected, observed/expected ratio (o/e) 0.74, 90% interval 0.68 to 0.81. Synonymous variants: 174 observed, 171.83 expected, observed/expected ratio (o/e) 1.01, 90% interval 0.89 to 1.15.
Homologues: Orthologues: chimpanzee OPCML (96% identical), pig OPCML (96% identical), dog OPCML (94% identical), mouse Opcml (94% identical), guinea pig OPCML (94% identical), rabbit OPCML (94% identical), rat Opcml (94% identical), macaque OPCML (86% identical), tropical clawed frog opcml (57% identical), zebrafish ntm (51% identical), Drosophila melanogaster DIP-kappa (32% identical), Caenorhabditis elegans rig-5 (29% identical), and 11 more. Paralogues in human: NTM (71% identical), LSAMP (52% identical), NEGR1 (48% identical), IGLON5 (47% identical), IGSF5 (16% identical).
Diseases named in the same sentence as OPCML in open-access papers:
OPCML is named in the same sentence as 66 diseases in open-access papers, as found by Europe PMC text mining. Sharing a sentence is not in itself a finding about the gene and the disease. The quoted sentences say what the papers report.
ovarian carcinoma (21 papers, 2004 to 2025). A malignant neoplasm originating from the surface ovarian epithelium. "In the early 2000s, OPCML was clearly shown to be silenced in the majority of ovarian cancer cases (via Knudson two-hit loss consisting of chromosomal loss (LOH) and somatic DNA methylation of two promoter CpG islands)." (PMID 40699804, 2025). "OPCML functions as a tumor suppressor and is silenced in over 80% of ovarian cancers by loss of heterozygosity and by epigenetic mechanisms." (PMID 36835855, 2023). "Odds ratios (ORs) and 95% confidence intervals (95% CIs) were used to determine the association of OPCML methylation with ovarian cancer risk." (PMID 33777925, 2021). "Previously, we showed that OPCML is inactivated predominantly by somatic methylation and loss of heterozygosity in more than 80% of ovarian cancer patients." (PMID 31316070, 2019). "OPCML is a tumour suppressor gene that is epigenetically silenced in ovarian cancer and is somatically mutated in various cancers." (PMID 31316070, 2019). "Evaluation of OPCML methylation as a diagnostic biomarker in clinical tissue samples has been performed in ovarian cancer, cholangiocarcinoma, prostate cancer, and lung cancer." (PMID 30832707, 2019). "OPCML is frequently inactivated by allelic loss and CpG island promoter methylation in epithelial ovarian cancer." (PMID 24179489, 2013). "OPCML, encoding an opioid-binding cell adhesion molecule, has been shown to be frequently methylated in ovarian cancer." (PMID 17967182, 2007). "Moreover, high OPCML expression was associated with longer survival in patients with HER2-positive ovarian cancer, and with better response to lapatinib treatment in breast cancer patients." (PMID 30832707, 2019). "Consequently, OPCML methylation in serum cfDNA has been assessed for its value as a diagnostic biomarker in ovarian cancer." (PMID 30832707, 2019). "In contrast, OPCML hypermethylation was first associated with epithelial ovarian cancer." (PMID 30555700, 2018). "The impact of OPCML expression in ovarian cancer cells supports strong relationships to external, microenvironment-facing signal networks." (PMID 40699804, 2025). "The goal of this study is to look more deeply into identifying the multi-functional impacts of OPCML in ovarian cancer and the consequences of having three Ig domains in order to better understand the integrated mechanism of its pleiotropic functions." (PMID 40699804, 2025). "In ovarian cancers, OPCML drives inactivation and degradation of the RTKs HER2, HER4, FGFR1, FGFR3, EPHA2, and AXL, and the specificity of this network is underscored by identification of a group of RTKs that are unaffected by OPCML." (PMID 40699804, 2025). "Using enrichment analyses, we reconstruct functional pathway impacts revealing interactions of OPCML, and then validate these in independent cohorts of ovarian cancer." (PMID 40699804, 2025). "Epigenetic silencing of OPCML is prevalent in ovarian cancers, with 82% of cases evidencing promoter methylation at two separate CpG dinucleotides upstream of the OPCML transcription start site." (PMID 40699804, 2025). "In another study, OPCML methylation was able to detect early ovarian cancer with sensitivity and specificity around 90%." (PMID 41301911, 2025). "Here we see a downstream tumor suppressor role for OPCML beyond the direct interaction with membrane RTKs previously reported, and validated orthogonally by previously reported pathways in independent ovarian cancer cohorts." (PMID 40699804, 2025). "From these functional gene sets, we then categorize genes by cellular location to compile a functional snapshot of the scope of OPCML’s influence in ovarian cancer." (PMID 40699804, 2025). "Ovarian cancer is also a disease of great unmet need, with poor outcomes for patients, and further insight into important tumor suppressors in ovarian cancer such as OPCML (inactivated in 82% of ovarian cancers) is an important justification for such research." (PMID 40699804, 2025).
ovarian carcinoma (continued). "In ovarian cancer, some of the most frequently methylated genes include OPCML (tumor suppressor activity), TES (involved in regulation of cell motility) and RASSF1A (tumor suppressor activity as well as an inhibitor of the anaphase-promoting complex)." (PMID 31608277, 2019). "Hypermethylation of OPCML was also observed in many cancers such as ovarian cancer, non-small-cell lung carcinoma, brain tumor, bladder cancer, and colorectal cancer." (PMID 30832707, 2019). "Previous study also reported that tumor suppressor OPCML inactivates AXL-dependent oncogenic signaling in ovarian cancer and also prevent transactivation of other RTKs such as EGFR and cMET44." (PMID 31043587, 2019). "We previously reported that OPCML interacts with a subset of RTKs and induces their degradation and/or dephosphorylation when re-expressed in ovarian cancer cells." (PMID 31316070, 2019). "Recently, OPCML was found to be a candidate tumor suppressor, which inhibited tumor growth in ovarian cancer and some other cancers including prostate cancer." (PMID 28407749, 2017). "OPCML has a tumor-suppressor function in mammary and ovarian cancer, and epigenetic inactivation of the gene induces oncogenic transformation of ovarian surface epithelial cells." (PMID 26042423, 2015). "OPCML, a broad tumor suppressor originally found in ovarian cancers, is found methylated in many lung cancer cell lines." (PMID 25347303, 2014). "The OPCML hypermethylation has been reported in several cancers for example, 33.3% of late stage ovarian cancer, 70% of hepatocellular carcinoma, 63.9% of invasive cervical cancer and 57–100% of multiple carcinomas and lymphomas." (PMID 21448164, 2011). "In this study, we assess the range of biological and cellular processes characterized and represented by transcripts that have synergistic associations impacting patient prognosis with RNA transcript expression levels of OPCML in ovarian cancer (stage IIIC, high grade serous carcinoma)." (PMID 40699804, 2025). "Here, we analyze RNA-Seq expression ratios in ovarian cancers from The Cancer Genome Atlas (TCGA) (189 subjects at Stage III) to identify genes that exhibit a cooperative survival impact (via Kaplan–Meier survival curves) with OPCML expression." (PMID 40699804, 2025). "When AXL is complexed with its ligand GAS6 in ovarian cancer cells, OPCML chaperones the AXL-GAS6 complex into external membrane lipid-raft domains where the complex becomes dephosphorylated through apposition to a raft restricted phosphatase and then targeted for ubiquitin-dependent degradation." (PMID 40699804, 2025). "In addition to ovarian cancer, OPCML is also hypermethylated in other solid tumors such as cervical cancer, lung, brain, live, bladder, prostate cancer, colorectal and gastric cancer, and lymphoma." (PMID 36835855, 2023). "A large number of putative suppressor genes that are silenced or activated by aberrant methylation have been identified in ovarian cancer, including hypermethylation of OPCML, RASSF1, CDKN2B as well as classical tumor suppressors BRCA1, p16 and MLH1, and hypomethylation of LINE-1, SLC6A12 and PRAME." (PMID 35710397, 2022). "To exemplify the power of NeDRex to extract biologically meaningful pathways from starting seeds, we used the ovarian cancer (OC) associated genes from NeDRexDB (AKT1, ALPK2, CDH1, CTNNB1, EPHB1, OPCML, PIK3CA, PRKN) and constructed disease module using the MuST algorithm." (PMID 34824199, 2021). "The CAM assay gave similar results and it also demonstrated that mutations in D2 and D3 affect the inhibition of tumorigenicity, pointing to the importance of the integrity of the three domains for OPCML’s full tumor suppressor activity in vivo at least in ovarian cancer." (PMID 31316070, 2019). "Moreover, there is a need to determine if OPCML has similar effects on receptor tyrosine kinases in the EAC cascade as has been observed in ovarian cancer." (PMID 30555700, 2018).
ovarian carcinoma (continued). "It is a well-established tumor suppressor of ovarian cancers that is frequently silenced by promoter hypermethylation and the detection of methylation of OPCML promoter in ovarian cancer tissues could have prognostic application." (PMID 27047543, 2016). "In a similar fashion, OPCML methylation may be useful in detecting ovarian cancer." (PMID 41301911, 2025). "However, we did not observe the associations of OPCML methylation with clinicopathological parameters and overall survival based on TCGA ovarian cancer data." (PMID 33777925, 2021). "However, the recently reported putative tumour suppressor in ovarian cancer, opioid-binding protein (OPCML), did not appear to have significant loss of expression in any of the samples studied here." (PMID 14760385, 2004). "The methylation of opioid-binding protein/cell adhesion molecules like OPCML, Runt-related transcription factor 3 (RUNX3), and tissue factor pathway inhibitor 2 (TFPI2) genes was studied in ovarian cancer patients using methylation-specific NGS." (PMID 38275400, 2024). "In the other fraction of ovarian cancer cases where OPCML silencing is not involved, there are other drivers and controls of tumor formation that are independent of the status of OPCML expression." (PMID 40699804, 2025).
schizophrenia (14 papers, 2012 to 2025). A major psychotic disorder characterized by abnormalities in the perception or expression of reality. "The genome-wide associate studies have linked the single nucleotide polymorphism of OPCML gene with schizophrenia and later studies using Opcml-deficient mice support this association." (PMID 40012565, 2025). "OPCML encodes neural cell adhesion molecules and SNPs in this gene have been linked to schizophrenia." (PMID 40307894, 2025). "Among the five IgLON family members, both NEGR1 and OPCML have been linked to major depressive disorder, schizophrenia, autism, anorexia nervosa, and Alzheimer’s disease." (PMID 38540422, 2024). "Polymorphisms in the OPCML gene have been linked to schizophrenia in GWAS studies in European patients and the association was later confirmed in a Thai population." (PMID 37895235, 2023). "OPCML is a susceptibility gene of schizophrenia, which can regulate spinal maturation and cognitive behavior through Eph-Cofilin signal transduction." (PMID 37308851, 2023). "Schizophrenia has been genetically associated with the opioid binding protein/cell adhesion molecule (OPCML), which is abundantly expressed in CNS, especially in the hippocampus and cerebral cortex." (PMID 34639067, 2021). "OPCML polymorphisms showed association with risks to schizophrenia and some other psychiatric disorders." (PMID 34639067, 2021). "Loci in NTM have been previously associated with bipolar disorder and schizophrenia in an independent GWAS, whereas OPCML has also been linked to schizophrenia." (PMID 32381021, 2020). "The expression of OPCML uniform transcript has been explored in our cohort previously in a study which aimed to measure the expression levels of genes identified as schizophrenia susceptibility genes by GWASs." (PMID 29434535, 2018). "Growing evidence suggests that the IgLON family of neural adhesion molecules LSAMP, NTM, NEGR1, and OPCML are important candidates in forming the susceptibility to schizophrenia (SCZ)." (PMID 29434535, 2018). "Alterations in 11q25 have already been associated with schizophrenia and schizophrenia susceptibility has been associated with SNPs in both OPCML and NTM, making it a considerable risk locus for dysfunctional neural regulation." (PMID 29434535, 2018). "Copy number variants in 11q25 where NTM and OPCML gene lie in close proximity have repeatedly been identified in patients with the diagnosis of schizophrenia." (PMID 29434535, 2018). "There was strong association between an intronic SNP of the OPCML gene (rs1784519) and the risk of schizophrenia in a Thai population P = 0.00036, odds ratio for the minor A allele: 2.11(1.57–2.84)]." (PMID 22643131, 2012). "Genetic variations associated with risks of schizophrenia have been investigated in opioid-binding protein/cell adhesion molecule (OPCML) gene using GWAS-discovered SNPs of Europeans ancestry." (PMID 22643131, 2012). "The two IgLON family members NEGR1 and OPCML share common links with several of them, such as schizophrenia, autism, and major depressive disorder." (PMID 38540422, 2024). "The opioid-binding protein/cell adhesion molecule (OPCML) is a schizophrenia susceptibility gene, and Opcml-deficient mice appear synaptic dysfunction and schizophrenia related behaviors." (PMID 39420375, 2024). "Although the role of OPCML in the pathophysiology of schizophrenia requires clarification, its crucial function in neurite outgrowth and spine maturation has been implicated through Eph-Cofilin signalling and F-actin polymerization." (PMID 37895235, 2023). "Differences in OPCML gene expression have also been detected in patients with schizophrenia, although protein level measurements from post mortem brains have not differed between patients and healthy controls." (PMID 31455857, 2020). "Based on Gwas meta-analysis from the Psychiatry Genomics Consortium, there is strongest evidence for the association of OPCML and NEGR1 genes with schizophrenia, compared to other IgLONs." (PMID 29434535, 2018).
schizophrenia (continued). "Two of these loci, represented by OPCML and an intergenic region (rs1602565) in chromosome 11, did not sit within one of the 108 schizophrenia risk loci identified by the PGC GWA study." (PMID 31455759, 2019). "No changes in the DLPFC of schizophrenic patients were found in the expression of OPCML uniform mRNA, similarly to our results, revealing no significant changes associated with schizophrenia in the expression of OPCML 1a and 1b isoforms." (PMID 29434535, 2018). "In earlier studies, OPCML gene at 11q25 has been found to be a schizophrenia susceptibility locus in the European and Thai populations and NTM has been significantly associated with schizophrenia in a genome-wide meta-analysis." (PMID 29434535, 2018).
cholangiocarcinoma (7 papers, 2019 to 2025). A carcinoma that arises from the intrahepatic biliary tree (intrahepatic cholangiocarcinoma) or from the junction, or adjacent to the junction, of the right and left hepatic ducts (hilar cholangiocarcinoma). "The discovery of OPCML as a tumour suppressor gene in epithelial ovarian cancer adds significant perspective to understanding epigenetic alterations in tumours, expanding upon potential diagnostic and therapeutic applications already explored in cholangiocarcinoma." (PMID 39057097, 2024). "Also, in a type of liver cancer (cholangiocarcinomas), OPCML enhanced the effect of bemcentinib in AXL-expressing cell lines." (PMID 40699804, 2025). "For example, significant differences in the methylation levels of OPCML and HOXD9 were observed in serum cell-free DNA from CCA patients, and these two genes can be used for the differential diagnosis between cholangiocarcinoma and other biliary diseases." (PMID 31889904, 2019).